ABCC1 (ATP binding cassette subfamily C member 1 (ABCC1 blood group))
Diseases named in the same sentence as ABCC1 in open-access papers (continued):
Sharing a sentence is not in itself a finding about the gene and the disease.
tumor (continued). "After protein and/or mRNA expression of ABCC1 and ABCB1 was established, the effects on pumps were examined by measuring ABCB1/ABCC1‐mediated calcein AM efflux in 2D‐cultured SK‐N‐AS cells to isolate the effect on tumor cells only." (PMID 37519014, 2024). "A link between ECM and ABCC1 was described in HT-29 cells, where the ECM from tumour cells was able to upregulate ABCC1, increasing their chemoresistance capacity." (PMID 38829241, 2024). "Most evidence is based on overexpression studies performed in tumor cell lines, and evidence that ABCC1 chemical inhibition or its genetic deletion increases chemosensitivity in animal models of squamous carcinogenesis is missing." (PMID 39201428, 2024). "One of the underlying mechanisms in tumor resistance is the aberrant activation of PI3K/AKT pathways that upregulates the expression of ABC transporters (P-gp/ABCB1, MRP1/ABCC1, and BRCP/ABCG2), and pro-survival molecules such as Bcl-2 and IAPs." (PMID 37627134, 2023). "Two studies suggest that to some extent, there is a correlation between levels of ABCC1 and tumor grade in ovarian cancer." (PMID 37838788, 2023). "More importantly, treatment with Se-MnP NPs led to down-regulation of MDR-related ABC family proteins (ABCB1 and ABCC1) to reverse MDR in HCT116/DR tumor cells." (PMID 36859296, 2023). "The levels of ABCC1 were found to be significantly higher in tumor tissue as compared to adjacent normal tissue (**p = 0.0012)." (PMID 36309544, 2022). "In hepatocellular carcinoma, circRNA PTGR1 regulates drug resistance to 5-fluorouracil (5-FU) and the growth tumor cells by regulating the miR-129-5p/ABCC1 axis." (PMID 35615158, 2022). "We analyzed the relative expression of ABC-transporters’ genes ABCB1, ABCC1, and ABCG2, transcription factor YB-1 and MVP gene associated with the distribution of xenobiotics in cytoplasm, in 70 tumor samples." (PMID 35328603, 2022). "The level of ABCC1 was significantly upregulated in tumor tissue as compared to adjacent normal in local cohort (*p = 0.035) and TCGA cohort (***p < 0.0001)." (PMID 36309544, 2022). "The protein levels of ABCC1 were also found to be high in tumor tissues as compared to adjacent normal tissues." (PMID 36309544, 2022). "In HCC, increased ABCC1 expression was related to increasing dedifferentiation, tumor size, and microvascular invasion." (PMID 35342392, 2022). "A significant upregulation of ABCC1 was observed in tumor tissues in both local as well as TCGA cohort." (PMID 36309544, 2022). "It was also related to enhanced murine breast tumour tumorigenesis and growth and a shorter survival of mice bearing tumours overexpressing ABCC1." (PMID 33801148, 2021). "A possible mechanism of ABCC1-regulated tumour growth is the elevated production and export of S1P (sphingosine-1-phosphate) by ABCC1." (PMID 33801148, 2021). "In summary, LINC00470 up‐regulated the expression of MYC by sponging miR‐134 to exert a tumour‐promoting effect, while miR‐134 affected the expression of ABCC1 by targeting MYC." (PMID 32916774, 2020). "We have demonstrated the ability of bile acids to increase doxorubicin cytotoxicity through the inhibition of ABCC1-mediated doxorubicin transport in various tumour cell lines in vitro." (PMID 29615646, 2018). "Where prior studies in erythrocytes have suggested that deoxycholic acid has an IC50 of 16 μM for inhibition of fluorescent substrate efflux, we have observed IC50’s ~10-fold higher for inhibition of ABCC1-mediated doxorubicin efflux from tumour cells." (PMID 29615646, 2018). "The present study is the first to show miRNA-133b enhancing the sensitivity of CRC to anti-tumor drugs by down-regulating ABCC1 expression." (PMID 28881788, 2017). "Recently, it was shown that miR-185-5p modifies CDDP-resistance by targeting ABCC1 (ATP-binding, cassette, subfamily C member 1), a relevant tumor suppressor." (PMID 29383199, 2017).
tumor (continued). "Our results indicated that miR-133b enhances the chemosensitivity of CRC to anti-tumor drugs by directly down-regulating ABCC1, suggesting a potential drug responsible for the reversal of MDR in CRC cells." (PMID 28881788, 2017). "Overexpression of ABCB1, ABCC1 and/or ABCG2 in tumor tissues is considered a major cause of limited efficacy of anticancer drugs." (PMID 27689338, 2016). "In each of the tumor, tumor-adjacent and tumor-distant tissues as well as in breast tissues from healthy women, the ABCC1 promoter was hypomethylated (methylation status < LOQ)." (PMID 27689338, 2016). "Overexpression of ABCB1, ABCC1 and ABCG2 in tumor tissues is considered a major cause of limited efficacy of anticancer drugs." (PMID 27689338, 2016). "In other instances, both patterns are present at the same time, as described for ABCC1 in a doxorubicin-resistant human tumor cell line." (PMID 22162766, 2011). "Furthermore, IHC staining revealed that ABCC1 was predominantly localized in the Golgi apparatus of C1GALT1 knockdown tumor cells, consistent with our in vitro findings." (PMID 39844613, 2025). "Collectively, these data demonstrated that KSQ‐4279 could widely and significantly potentiate the chemotherapeutic cytotoxicity of traditional agents in the ABCB1‐, ABCG2‐, and ABCC1‐induced MDR tumor cells in vitro." (PMID 41328326, 2025). "We investigated whether C1GALT1 contributed to drug resistance and tumor growth in OS cells through the ABCC1 pathway." (PMID 39844613, 2025). "Similarly, research demonstrated that the exosome secreted by M2 macrophages delivered circTEX2 to GC cells and relieved its inhibition of drug effector protein ABCC1 by adsorption of miR-145, thus enhancing the resistance of tumor cells to DDP." (PMID 40309240, 2025). "ABCC1 knockdown reversed C1GALT1‐mediated tumor growth by 36% in response to doxorubicin challenge." (PMID 39844613, 2025). "We observed a correlation between p63 and ABCC1 protein levels in 70 tumor samples." (PMID 39201428, 2024). "ABCC1 effluxes both hydrophobic and hydrophilic antineoplastic agents, including vincristine, doxorubicin, etoposide, and anthracyclines, thereby reducing drug accumulation within the cell and allowing for tumor resistance." (PMID 37438132, 2023). "In that context, it has been described that ABCC1 may be upregulated in both physiological and tumor microenvironments during the acquisition of an SP phenotype." (PMID 37047018, 2023). "Another reason for the low efficiency of cancer treatment is the development of acquired resistance of tumor cells to chemotherapeutic agents, which is frequently caused by the overexpression of specific drug-transporting proteins—ABCB1 (P-glycoprotein), ABCC1 (MRP-1), or ABCG2 (Bcrp)." (PMID 36986696, 2023). "Up regulation of ATP-binding cassette(ABC) transporter super family proteins such as ABCB1, ABCG2 and ABCC1 which pump chemotherapeutic drugs out of tumor cells thereby reducing intracellular drug accumulation have been observed as the most common mechanism of chemotherapy resistance." (PMID 37654838, 2022). "First, we detected the expression levels of ABCC1 in the selected set of primary tumor explants." (PMID 36559089, 2022). "ABCC1-overexpressing tumor cells accumulated less As2O3 than wild-type cells." (PMID 29535630, 2018). "Moreover, our studies are the first to describe the ability of bile acids to affect ABCC1 activity and doxorubicin sensitivity in drug-resistant tumour cells in culture and in cells genetically engineered to overexpress the ABCC1 transporter." (PMID 29615646, 2018). "By inhibiting ABCC1 specifically, β-cholanic acid might augment accumulation of doxorubicin in ABCC1-expressing tumours, while retaining ABCB1’s ability to protect sensitive brain tissues to the damaging effects of doxorubicin." (PMID 29615646, 2018). "Furthermore, our results show that ABCC1 correlated with SPHK1 expression and suggests that S1P is exported by ABCC1 to the tumor microenvironment." (PMID 30018456, 2018).
tumor (continued). "Many studies have reported that the three monomers of curcuminoids reverse the overexpression of ABC transporters including ABCB1, ABCG2, and ABCC1 in drug resistant tumor cells without causing systemic toxicity." (PMID 28591733, 2017). "Therefore, miR-133b enhances the chemosensitivity of CRC cells to anti-tumor drugs by directly down-regulating ABCC1." (PMID 28881788, 2017). "ABCC1 exhibited a 1.8-fold higher median expression in tumor samples." (PMID 25275603, 2014). "The MRP most generally present in cells, MRP1 (ABCC1), has never been conclusively linked to resistance in either mouse model tumours or human clinical samples." (PMID 22724067, 2012). "Based on its role in modulating the export of diverse endogenous metabolites, ABCC1 targeting might impact other tumor-related phenomena that are not directly linked to its ability to modulate the extracellular efflux of anti-neoplastic agents." (PMID 39201428, 2024). "In line with this hypothesis, we observed a significant increase in ABCC1 expression in different SCCs, including skin, head and neck and cervical SCCs, which are characterized by keratinocyte hyper-proliferation and a pro-inflammatory tumor microenvironment." (PMID 39201428, 2024). "ABCC1, also known as multidrug resistance-associated protein 1 (MRP1), plays a significant role in the recognition and efflux of both hydrophobic and hydrophilic antineoplastic agents, resulting in decreased drug accumulation within tumor cells and contributing to the development of MDR." (PMID 39403600, 2024). "Reducing intracellular drug accumulation is an important approach to regulate tumor drug resistance, and ATP‐binding cassette (ABC)‐mediated drug efflux is associated with multidrug resistance in OS, and MDR‐related protein‐1 (MRP1, also known as ABCC1) is a major target of ABC." (PMID 37441462, 2023). "For TMZ specifically, the inhibition of ABCB1, ABCG2, ABCE1, ABCC1, and ABCB5 has seen significant decreases in either GBM tumor volume/weight by (~40–90% reduction), or significant increases in median survival (~1.3- to 5-fold increase)." (PMID 39861164, 2025). "The use of shRNAs, micro-RNAs, and monoclonal antibodies that directly inhibited ABCE1, ABCC1, and ABCB5 in vivo was followed by decreased tumor growth." (PMID 39861164, 2025). "The viability of tumor specimens was analyzed by MTT assay and an Image Analysis System, and the expression of ABCB1, ABCG2, and ABCC1 proteins in specimens was synchronously detected via western blot assays." (PMID 41328326, 2025). "Members such as ABCB1 (MDR1), ABCC1 (MRP1), and ABCG2 (BCRP) are frequently overexpressed in drug-resistant tumours and CSC subpopulations." (PMID 41321388, 2025). "By day 28, tumor volume analyzed by calipers indicated a 46% increase in the C1GALT1 overexpression group compared to the control group, while ABCC1 knockdown reduced tumor growth by 38%, aligning with the reduction observed in the IVIS analysis." (PMID 39844613, 2025). "Among the pumps found in tumor stem-like cells, ABCB1, Multidrug Resistance 1 (MDR1), ABCC1, Multidrug Resistance Protein 1 (MRP1), and ABCG2, Breast cancer-resistance protein 1 (BCRP1) are the most well-known." (PMID 38002496, 2023). "We then estimated chemotherapy-associated drug-resistant genes, including ABCB1, ABCC1 and ABCG2, and found that curcumol significantly reversed the mRNA levels of CDDP-induced ABCB1, ABCC1 and ABCG2 genes in the tumor tissue." (PMID 35889217, 2022). "We clearly observed c-MYC recruitment to the promoter of ABCC1 and ABCC4 in tumours from Eμ-Myc mice compared with controls that correlate with its higher gene expression." (PMID 35326669, 2022). "It was observed in the TCGA database that ABCC1, ABCC4, ABCC5, and ABCC10 were significantly upregulated in tumor tissues, while ABCC6 and ABCC7 were downregulated in HCC tissues." (PMID 35342392, 2022).
tumor (continued). "Expression of two key drug transporters i.e., ABCC1 and ABCG2 were analysed in tumor and adjacent normal breast tissues in local as well as TCGA cohort." (PMID 36309544, 2022). "In the qRT-PCR assays of 48 PDAC tumor samples obtained in our department, a significant positive correlation was observed between ATF4 expression and ABCC1 expression (R = 0.3873, p = 0.0001)." (PMID 33782384, 2021). "Studies of drug-resistant cell lines derived from human neoplasms identified amplifications of at least 13 ABC transporter genes, including ABCB1, ABCC1 and ABCC4." (PMID 32206879, 2020). "Three of the ABC transporters were commonly reported to be responsible for MDR in various tumor types: P-glycoprotein (Pgp, ABCB1), multidrug resistance protein 1 (MRP1, ABCC1), and breast cancer resistance protein (BCRP, ABCG2)." (PMID 29301374, 2018). "The stemness‐associated genes were analysed using RT‐qPCR, and the results showed that the mRNA levels of Nanog, Sox2, Oct4, CD44, CD133, ABCB1, ABCC1, ABCG2 and Notch1 were significantly increased in RCC tumour spheres compared with parental cells." (PMID 30246456, 2018). "In contrast to the ABCC1 promoter which was found to be hypomethylated (methylation status < LOQ) in all tumor, tumor-adjacent and tumor-distant tissues, the ABCB1 and ABCG2 promoters were found to be methylated very frequently." (PMID 27689338, 2016). "We analyzed for expression of five ABC transporters ABCB1, ABCC1, ABCC2, ABCC3 and ABCG2 using immunohistochemistry in 103 pre-treatment tumor specimens obtained from patients with CHL." (PMID 22871336, 2012). "Associations between UGT1A1 (TA)n, UGT1A1 –3156G>A, SLCO1B1*1b 388A>G and ABCC1 IVS11 –48C>T genotypes and drug response (tumour DS, ypT0, OS and RFS) to 5-FU+irinotecan were evaluated for the 35 patients of group 2." (PMID 22045187, 2011). "Several upregulated ABC transporters, such as ABCA12, ABCC1 and ABCC4, were also identified, which may contribute to immune-modulatory molecule efflux and further alter the tumor microenvironment." (PMID 39860532, 2025). "Moreover, NRF2-driven upregulation of ABCC1 (MRP1) can deplete intracellular GSH, further contributing to ferroptosis in tumor cells." (PMID 40724908, 2025). "Mechanistically, POLR2J4 knockdown reduced the expression of drug resistance genes (ABCB1, ABCC1, BCL2), decreased serum levels of IL-6 and TGF-β1, and downregulated TGF-β1 and PD-L1 in tumor tissues, highlighting its role in establishing an immunosuppressive, drug-resistant microenvironment." (PMID 40661083, 2025). "In non-small cell lung cancer (NSCLC) the efficacy of chemo-immunotherapy is affected by the high expression of drug efflux transporters as ABCC1 and by the low expression of ABCA1, mediating the isopentenyl pyrophosphate (IPP)-dependent anti-tumor activation of Vγ9Vδ2 T-lymphocytes." (PMID 39107857, 2024). "Furthermore, in a panel of 70 cSCC tumor samples and in CESC and LUSC datasets, we observed a strong correlation between p63 and ABCC1 expression, strengthening the functional link between these two proteins." (PMID 39201428, 2024). "Specifically, EVs from drug-resistant tumor cells can horizontally transfer various components, such as drug-efflux pumps (e.g., ABCB1, ABCC1), miRNAs (e.g., miR-21-5p, miR-222), and regulatory proteins (e.g., TrpC5, EGFR), to drug-sensitive cells, thereby spreading a drug-resistant phenotype." (PMID 39403600, 2024). "What is most important is that these compounds only slightly influenced the expression of the ABCB1, ABCC1, and ABCC2 genes and the level of the MDR1 protein in the studied colon LS 174T and prostate DU 145 tumor cells, especially for the C-2028, C-2045, and C-2053 derivatives." (PMID 39683740, 2024). "Moreover, metastasis presented higher ABCC1, ABCC3 and ABCC4 expression and lower SLC22A1 and ABCC10 expression than the primary tumor." (PMID 36982681, 2023).
tumor (continued). "Finally, in vivo studies further demonstrated that Se-MnP and OX@Se-MnP NPs reversed MDR in tumor cells and induced tumor apoptosis to suppress tumor growth by down-regulating the expression of MDR-related ABC transporters proteins (ABCB1, ABCC1 and ABCG2)." (PMID 36859296, 2023). "Notably, we also observed, for the first time, a significant increase in ABCC1 activity following EMT, denoting a possible practical gain in the ability of extruding chemotherapy drugs or other substrates by tumor cells undergoing this process." (PMID 37047018, 2023). "ABCB1, ABCC1\2\3, ABCG2, ERCC1, XRCC1\2 can induce tumor chemo-resistance and radio-resistance." (PMID 37283789, 2023). "However, the expression levels of ABCC1 and ABCC2 drug efflux transporters were very similar between the non-tumor-initiating subpopulation (CD44−CD133- and CD44−CD133+ Caco-2 cells) and the tumor-initiating subpopulation (CD44+CD133+ Caco-2 cells)." (PMID 35433695, 2022). "It has shown downregulation of P-gp, BCRP, MRPs, and ABC transporter genes (ABCB1, ABCG2, and ABCC1), which may reverse MDR in tumor cells." (PMID 34680470, 2021). "Quercetin has been also reported to modulate the activity of some members of the multidrug-resistance transporters family, such as P-gp, ABCC1, ABCC2, and ABCG2, and the activity of ecto-5′-nucleotidase (NT5E/CD73), a key regulator in some tumor processes such as invasion, migration, and metastasis." (PMID 33918012, 2021). "In this study, we provide strong evidence that bile acids can selectively reduce doxorubicin accumulation into ABCC1-expressing (but not ABCB1-expressing) tumour cells." (PMID 29615646, 2018). "Given its role in promoting the extracellular efflux of diverse chemotherapeutic drugs, such as daunorubicine, etoposide and camptothecine, it is not surprising that the most studied function of ABCC1 in human pathology is related to its capacity to induce chemoresistance in tumor cells." (PMID 39201428, 2024). "We identified some mutation markers specific to tumor types, including some typical tumor‐related genes (e.g., TP63, ABCC1, ABCC5, and TFDP1 in ESCA) as well as numerous noncoding genes (e.g., NPSR1‐AS1 and AC079466.1 in HCC) and pseudogenes (e.g., SDHAP3 and TPTEP1 in LUAD)." (PMID 38010945, 2024). "Human tumor transcriptomic data for 377 HCC patients also show a positive correlation of multiple ABC transporters including the ABCB1, ABCC3, ABCC9 and ABCG2 with GHR expression, while ABCC1,ABCC4 and ABCG1 levels correlated with IGF1R expression, confirming our in vivo observations." (PMID 35865483, 2022). "We, therefore, hypothesized that LPA decreases Taxol-induced accumulation of the cells in G2/M by stimulating Taxol efflux through ABCB1 (multidrug resistance gene 1), p-glycoprotein (ABCC1) or ABCG2, since these transporters account for a major portion of drug resistance in human tumor cells." (PMID 21647386, 2011). "Furthermore, ferroptosis-related genes with copy number amplification (including FADS2, NQO1, ABCC1, ACSF2, HMOX1, FANCD2 and SQLE) demonstrated higher expression in tumour tissues, and those with copy number deletion (including CRYAB, ACSL3, ZEB1) demonstrated lower expression in tumour tissues." (PMID 35145965, 2022). "Statistical analysis performed with the U Mann–Whitney test showed a statistically significantly higher expression level of the ABCB9 (p = 0.000), ABCC1 (p = 0.009), and ABCC6 (p = 0.000) genes in patients without tumor cell invasion into fat tissue." (PMID 36674773, 2023). "A heterozygous ABCC1 single nucleotide substitution (SNS), p1088P/L was present in the MN1-rearanged tumor lacking MN1-BEND2 fusion from a male patient (C16)." (PMID 35440587, 2022). "Interestingly, other ABC transporter genes that have been described to confer resistance in cell lines with acquired doxorubicin (e.g., ABCC1, ABCC2, and ABCG2) were not related to inherent anthracycline resistance in this panel of tumor cell lines." (PMID 40723843, 2025).